ZIC1 (Zic family zinc finger 1)
Diseases named in the same sentence as ZIC1 in open-access papers (continued):
Sharing a sentence is not in itself a finding about the gene and the disease.
cancer (22 papers, 2009 to 2026). A tumor composed of atypical neoplastic, often pleomorphic cells that invade other tissues. "Our study identified DNAme of ANKRD34 and ZIC1 as new cancer susceptibility loci for RCC development." (PMID 35628134, 2022). "Thus, the newly identified ANKRD34B and ZIC1 cancer loci double the number of age-independent susceptibility loci detected in normal kidney tissue, and strengthen the hypothesis that more as yet unidentified loci may exist." (PMID 35628134, 2022). "ZIC1 is therefore a stark example of how the same gene can have distinct driver mechanisms in highly similar cancers depending on their specific lineage of origin." (PMID 39753768, 2025). "We identified 30 cancer-specific normal-invariant genes, including Zic family members (ZIC1, ZIC4, and ZIC5), DPPA2, PRSS56, ELF5, and FGF18, most of which were cancer-associated genes." (PMID 39969322, 2024). "Our results align with these findings, as we revealed strong hypermethylation of ZIC1 in carcinomas compared to BOTS in most regions of the gene (GR file)." (PMID 39456618, 2024). "Both ANKRD34B and ZIC1 have been reported in a pan-cancer analysis to be targets of PRC2, with hypermethylated CGIs." (PMID 35628134, 2022). "HHEX caused a repression of a series of neural stemness genes or/and genes promoting cancer, Sox1, Sox2, Myc, Cdh2, Vim, Hes1, Zic1, Pax6, Ezh2, and Lsd1." (PMID 34595169, 2021). "Further study is required to illustrate the mechanisms by which ZIC1 regulates these potential pathways in cancer progression." (PMID 21347233, 2011). "We found that siRNA-mediated knockdown of ZIC1 suppressed the ability of OTBCs to form spheroids in vitro, outlining an important role of ZIC1 as a potential oncogene in claudin-low carcinomas." (PMID 21952072, 2011). "In several cancers like thyroid, gastric, and colorectal cancers, ZIC1 was found to be silenced by methylation, and upon overexpression in cancer cells, it was shown to inhibit cell proliferation, induce cell cycle arrest, and apoptosis by blocking the activities of the PI3K/Akt and MAPK pathways." (PMID 40952541, 2025). "Taking into consideration that both regions demonstrate hypermethylation in a large number of cell line models of important human cancers, these findings conceivably have a broader relevance and, in the case of ZIC1, this has already been confirmed in the literature." (PMID 35628134, 2022). "Subsequently, we validated the most potent markers (ASCL1, LHX8, SST, WDR17, ZIC1 and ZNF582) in a large independent series, confirmed the accuracy (AUC = 0.89) and showed that high methylation levels are associated with progression towards cancer." (PMID 33580586, 2021). "However, little is known about how ZIC1 regulates signal pathways and their related downstream targets in cancer progression." (PMID 22799764, 2012). "Fourthly, previous studies revealed that both COL2A1, which encodes a component of type-II collagen and collages, and ZIC1 could suppress cancer metastasis by regulating the signaling pathway of the extracellular collagen-derived antiangiogenic factor and Wnt signaling pathway respectively." (PMID 36081518, 2022). "ZIC1 and ZIC4 genes are frequently subject to epigenetic silencing through DNA hypermethylation at their promoter regions in several cancers." (PMID 40952541, 2025). "For the hyper-methylated gDMs, down-regulated expression in cancer samples was observed for CACNB2 and ZIC1." (PMID 36329447, 2022). "The optimal marker panel (ASCL1 and ZIC1; AUC = 0.85 for AIN3+) detected 98% of cancers at 79% specificity." (PMID 33580586, 2021). "ZIC1 and ZIC4 are known to be regulators of the SHH signaling pathway by antagonizing the transcriptional activity of Gli proteins, and arefound to be silenced by hypermethylation in several types of cancers." (PMID 40952541, 2025).
cancer (continued). "As a result, seven DEGs correlated with more than 10 TR-DDR genes (r>0.3) in at least 10 cancers were regarded as candidate genes, including COL2A1 (the R ranged from 0.39 to 0.60), MAGEA4 (0.24–0.62), FCRL4 (0.33–0.62), ZIC1 (0.24–0.33), LCN15 (0.20–0.41), PRSS3 (0.24–0.35), CSAG1 (0.31–0.38)." (PMID 36081518, 2022). "Common cell line models of prostate, breast, urothelial, renal, and other cancers were used to estimate whether hypermethylation of ANKRD34B and ZIC1 can occur with relevant frequency in human tumors." (PMID 35628134, 2022).
infection (1 paper, 2024). The state of being infected such as from the introduction of a foreign agent such as serum, vaccine, antigenic substance or organism. "Increased expression of neuromotor-related genes such as Adam22, Cacnb4 and Zic1 (activated by NF1_LV infection) and ChAt (activated by NF45_LV infection) could explain PAM symptoms such as muscle weakness and seizures." (PMID 39735262, 2024).
neurological diseases (1 paper, 2014). "Numerous splicing factors identified here have been reported to have functions in neuronal differentiation, neurological diseases, or synaptic plasticity, such as ELAVL2, ZIC1, A2BP1 (official gene symbol Rbfox1), and FUS." (PMID 24758366, 2014).
ZIC1 also shares sentences with these, for which no sentence is quoted: hepatocellular carcinoma (4 papers); brain tumors (2); neurodevelopmental disorder (2); scoliosis (2); astrocytoma (1); breast tumors (1); Cerebellar dysplasia (1); Cerebellar hypoplasia (1); cervical disease (1); clear cell renal cell carcinoma (1); Coronal craniosynostosis (1); craniosynostosis 4 (1); craniosynostosis 6 (1); desmoid tumor (1); diabetes (1); Distichiasis (1); epilepsy (1); ganglioglioma (1); Hematuria (1); learning disability (1); Lipedema (1); liver disease (1); lymph node metastasis (1); mesenchymal neoplasms (1); neurinoma (1); oligodendroglioma (1); ovarian tumors (1); Parkinson disease (1); postmenopausal osteoporosis (1); primitive neuroectodermal tumor (1).
A further 2 diseases each share a sentence with ZIC1 in 1 paper.